STRAP (serine/threonine kinase receptor associated protein)
Description:
The SMN complex catalyzes the assembly of small nuclear ribonucleoproteins (snRNPs), the building blocks of the spliceosome, and thereby plays an important role in the splicing of cellular pre-mRNAs. Most spliceosomal snRNPs contain a common set of Sm proteins SNRPB, SNRPD1, SNRPD2, SNRPD3, SNRPE, SNRPF and SNRPG that assemble in a heptameric protein ring on the Sm site of the small nuclear RNA to form the core snRNP (Sm core). In the cytosol, the Sm proteins SNRPD1, SNRPD2, SNRPE, SNRPF and SNRPG are trapped in an inactive 6S pICln-Sm complex by the chaperone CLNS1A that controls the assembly of the core snRNP. To assemble core snRNPs, the SMN complex accepts the trapped 5Sm proteins from CLNS1A forming an intermediate. Binding of snRNA inside 5Sm triggers eviction of the SMN complex, thereby allowing binding of SNRPD3 and SNRPB to complete assembly of the core snRNP. STRAP plays a role in the cellular distribution of the SMN complex. Negatively regulates TGF-beta signaling but positively regulates the PDPK1 kinase activity by enhancing its autophosphorylation and by significantly reducing the association of PDPK1 with 14-3-3 protein.
Synonyms: MAWD; UNRIP; pt-wd
Tractability: PROTAC: ubiquitination databases record sites on it; its protein half-life has been measured.
Gene: Protein-coding gene on chromosome 12 (15,882,356 to 15,903,478, forward strand). Ensembl gene ENSG00000023734.
Subcellular location: Cytoplasm; Nucleus
Subcellular location (Human Protein Atlas): Cytosol; Cell Junctions
Pathways (Reactome):
Cell-Cell communication: Positive Regulation of CDH1 Gene Transcription
Signal Transduction: Downregulation of TGF-beta receptor signaling
Gene Ontology:
Molecular function: protein binding; RNA binding; mRNA binding; signaling receptor binding; U2 snRNP binding
Biological process: maintenance of gastrointestinal epithelium; negative regulation of transforming growth factor beta receptor signaling pathway; spliceosomal snRNP assembly; alternative mRNA splicing, via spliceosome; cell differentiation; mRNA splicing, via spliceosome; protein-RNA complex assembly
Cellular component: cytoplasm; cytosol; SMN complex; SMN-Sm protein complex; nucleus
Genetic constraint (gnomAD): Loss-of-function variants: 12 observed, 34.27 expected, observed/expected ratio (o/e) 0.35, 90% interval 0.22 to 0.57. The upper end of that interval is the gene's LOEUF score, 0.57, which puts it in group 2 of 6, group 1 being the genes least tolerant of losing a copy. Missense variants: 230 observed, 357.08 expected, observed/expected ratio (o/e) 0.64, 90% interval 0.58 to 0.72. Synonymous variants: 116 observed, 128.11 expected, observed/expected ratio (o/e) 0.91, 90% interval 0.78 to 1.06.
Homologues: Orthologues: chimpanzee STRAP (99% identical), macaque STRAP (99% identical), rabbit STRAP (98% identical), rat Strap (98% identical), dog STRAP (98% identical), mouse Strap (98% identical), guinea pig STRAP (97% identical), pig STRAP (97% identical), tropical clawed frog strap (78% identical), zebrafish strap (77% identical), Drosophila melanogaster wmd (56% identical).
Diseases named in the same sentence as STRAP in open-access papers:
STRAP is named in the same sentence as 41 diseases in open-access papers, as found by Europe PMC text mining. Sharing a sentence is not in itself a finding about the gene and the disease. The quoted sentences say what the papers report.
colorectal cancer (11 papers, 2015 to 2025). A primary or metastatic malignant neoplasm that affects the colon or rectum. "In colorectal cancer patients, the upregulation of STRAP is associated with worse survival following adjuvant therapy." (PMID 40558481, 2025). "A recent study demonstrates that the serine-threonine kinase receptor associated protein (STRAP) is oncogenic and regulates stemness behavior and drug response in colorectal cancer via mediating the epigenetic activation of Notch signaling." (PMID 33681228, 2021). "In clinical specimens, STRAP expression increased in colorectal cancers and its high expression was associated with poor prognosis." (PMID 29652830, 2018). "STRAP has been implicated in maintaining colorectal cancer cell stemness." (PMID 34206917, 2021). "In colorectal cancer, silencing STRAP can form inhibitory chromatin domains to suppress the activation of the Notch1-Hes1 axis, weaken CSC self-renewal, and enhance chemosensitivity." (PMID 40755759, 2025). "In contrast, patients carrying tumors with normal or low STRAP expression benefited from the treatment, suggesting its direct involvement in colorectal cancer progression and chemoresistance." (PMID 40558481, 2025). "The upregulation of STRAP expression is correlated with worse survival in colorectal cancer following post-adjuvant therapy." (PMID 40558481, 2025). "STRAP expression supports tumorigenicity by promoting the Wnt/β-catenin pathway in colorectal cancer." (PMID 34206917, 2021). "The same investigators also demonstrated an increase in the sensitivity to 5-FU and oxaliplatin in colorectal cancer following shRNA STRAP knockdown." (PMID 34206917, 2021). "Jin and colleagues found that STRAP inhibition with shRNA decreased CD133 positive colorectal cancer cells and tumorsphere forming ability." (PMID 34206917, 2021). "In colorectal cancer, STRAP knockdown with shRNA led to decreased tumor growth and metastasis in vivo." (PMID 34206917, 2021). "A recent study also implicates that STRAP has a role in the progression of colorectal cancers (CRCs)." (PMID 29849900, 2018). "The NOTCH pathway is activated in colorectal cancer cells also through epigenetic mechanisms, orchestrated by the overexpression of the signaling scaffold protein STRAP." (PMID 29652830, 2018). "STRAP expression was elevated in all stages of colorectal cancer, and the tumor growth was inhibited in heterozygous STRAP knockout mice." (PMID 29849900, 2018). "This study provides a rationale for targeting STRAP for therapeutic intervention in colorectal cancers." (PMID 26910283, 2016). "In summary, these studies demonstrate novel mechanistic insights into the functions of STRAP in colorectal cancer invasion and metastasis." (PMID 26910283, 2016). "However, nothing is known about the role of STRAP in regulating Wnt/β-catenin signaling in colorectal cancer." (PMID 26910283, 2016). "Based on the previous observations that the expression of STRAP is upregulated in human colorectal cancers and our findings that STRAP stabilizes β-catenin, we predicted that the expression levels of STRAP and β-catenin would be functionally correlated in colorectal cancers." (PMID 26910283, 2016). "We observed in 130 colorectal cancer specimens that STRAP is upregulated in about 70% cases." (PMID 26910283, 2016). "STRAP promoted the stem cell-like characteristics of colorectal cancer cells by activating the NOTCH pathway and the silencing of STRAP in these cells resulted in decreased stem cell phenotype." (PMID 34206917, 2021). "In colorectal cancer patients, STRAP expression has been found to be highest in Stage I, and its levels are maintained in Stage II/III/IV, where STRAP may contribute to its oncogenic and chemoresistance functions." (PMID 40558481, 2025).
colorectal cancer (continued). "In addition, STRAP binds with GSK-3β and stabilizes β-Catenin by inhibiting its phosphorylation by GSK-3ß and ubiquitin-dependent degradation, resulting in stimulation of Wnt/β-Catenin signaling and the expression of its downstream targets in colorectal cancer cells." (PMID 40558481, 2025).
colon carcinoma (7 papers, 2013 to 2025). "To investigate the effect of these mutations on STRAP-induced stabilization of β-catenin, we chose three different human colon cancer cell lines, SW480, HCT116 and RKO having different mutational status in APC and β-catenin genes." (PMID 26910283, 2016). "Therefore, future studies will determine whether STRAP is a molecular target for the treatment of colon cancer in patients with APC mutation or Wnt/β-Catenin activation." (PMID 40558481, 2025). "In colon cancer, STRAP recruits MEK1/2 and enhances the interaction between MEK1/2 and ERK1/2 to activate the phosphorylation of ERK1/2." (PMID 38365721, 2024). "STRAP is up-regulated in 60% colon carcinomas and demonstrates oncogenic function in multiple tumors." (PMID 29783958, 2018). "In contrast, STRAP stabilizes β-catenin in colon cancer cell lines with wild type APC and β-catenin." (PMID 26910283, 2016). "Strikingly, STRAP is upregulated in colon and lung carcinomas and STRAP upregulation in colon tumors correlates with EWS expression." (PMID 24082883, 2013). "Our previous study has shown that STRAP is upregulated in colon carcinoma and upregulation of STRAP in human cancers may provide growth advantage to tumor cells via TGF-β-dependent and TGF-β-independent mechanisms." (PMID 26910283, 2016). "To investigate the role of STRAP on invasion and metastasis in CRC, we stably knocked down STRAP in murine colon carcinoma cell lines MC38 and CT26 as determined by western blotting." (PMID 26910283, 2016). "STRAP can interact with MEK1/2 and is involved in the interaction between MEK1/2 and ERK1/2, which is required for the phosphorylation of the ERK pathway in colon cancer." (PMID 38365721, 2024).
lung carcinoma (6 papers, 2013 to 2024). "Serine-threonine kinase receptor-associated protein (STRAP), a member of the family of WD-40 repeat proteins, is reported as an oncogene in many cancers, including lung cancer, intestinal cancer, and hepatocellular carcinoma." (PMID 38365721, 2024). "In lung cancer, STRAP led to tumor progression by downregulating tumor suppressors, E-cadherin, and the CDK inhibitor, p21Cip1, through the modulation of the transcription factor Sp1." (PMID 34206917, 2021). "STRAP is overexpressed in several malignancies, including colorectal and lung cancer and the pediatric bone cancer, osteosarcoma." (PMID 34206917, 2021). "Our previous study showed that STRAP is upregulated both in colon and lung carcinomas and promote tumorigenicity." (PMID 26910283, 2016). "We have genetically engineered a series of murine and human CRC and lung cancer cell lines to investigate the effects of STRAP on cell migration and invasion in vitro, and on tumorigenicity and metastasis in vivo." (PMID 26910283, 2016). "All these evidences prompted us to investigate whether STRAP has any effect on stabilizing β-catenin in lung cancer." (PMID 26910283, 2016). "Besides, our previous studies have shown that STRAP is up regulated in 78% of lung carcinomas." (PMID 26910283, 2016). "Our previous studies have shown that STRAP is upregulated in CRC and lung cancer, and can provide growth advantage to tumor cells via TGF-β-dependent and -independent mechanisms." (PMID 26910283, 2016).
breast carcinoma (3 papers, 2013 to 2024). "For example, hsa_circ_0007990 inhibits YBX1 protein to promote breast cancer growth, while CircPCNXL2 is reported to promote cholangiocarcinoma metastasis by interacting with STRAP." (PMID 39581695, 2024). "Nm23-H1 was previously reported to affect proliferation and differentiation of cervical cancer and breast carcinoma cell lines, suggesting that STRAP may also contribute to the progression of cervical and breast tumors." (PMID 29849900, 2018). "Furthermore, STRAP protein expression is elevated in 60% of colorectal, 78% of lung, and 46% of breast carcinomas." (PMID 29849900, 2018).
hepatocellular carcinoma (3 papers, 2021 to 2025). A malignant tumor that arises from hepatocytes. "STRAP has been implicated as an important oncogenic factor in hepatocellular carcinoma (HCC), specifically through its ability to modulate the Wnt/β-Catenin signaling pathway, which is crucial for cell proliferation, differentiation, and cancer progression." (PMID 40558481, 2025). "Additionally, the loss of STRAP in HCC cells leads to decreased metabolic activity and disruptions in cell cycle progression, underscoring its multifaceted role in driving hepatocellular carcinoma progression." (PMID 40558481, 2025). "In addition, STRAP knockout in hepatocellular carcinoma decreased mRNA abundance of stemness markers and liver progenitor genes, including AXIN2, LGR5, CD133, and CD44." (PMID 34206917, 2021). "STRAP increased cancer cell stemness in colorectal and hepatocellular carcinoma." (PMID 34206917, 2021). "In addition, the knockdown of STRAP with shRNA in hepatocellular carcinoma resulted in decreased tumorigenicity and metastasis." (PMID 34206917, 2021). "However, Wu and colleagues found that knockdown of STRAP utilizing siRNA promoted hepatocellular carcinoma tumorgenicity in vitro and in vivo, suggesting that STRAP’s role in cancer may not be tumor-specific." (PMID 34206917, 2021).
neuroblastoma (3 papers, 2012 to 2025). Neuroblastoma (NB) is the most common solid, extracranial childhood tumor. "Increased STRAP expression has been shown to be associated with poor prognosis in neuroblastoma patients." (PMID 40558481, 2025). "In the current study, genetic evaluation demonstrated a downregulation of genes associated with neuroblastoma stemness following the knockout of STRAP." (PMID 34206917, 2021). "STRAP knockout downregulates various genes associated with tumor growth and progression, with notable downregulation of platelet-derived growth factor receptor ß (PDGFRβ), a highly upregulated oncogene in neuroblastoma." (PMID 40558481, 2025). "STRAP is overexpressed in other cancers and has been associated with a more aggressive phenotype; this provides an exciting avenue for future work to investigate STRAP expression levels in patient neuroblastoma specimens as a potential predictor for high-risk disease." (PMID 34206917, 2021). "STRAP silencing using small RNA (siRNA or shRNA) in neuroblastoma cells (SK-N-AS and SK-N-BE) resulted in decreased tumor cell viability, growth, stemness, and motility in vitro and tumor growth in vivo." (PMID 40558481, 2025). "In order to further validate our findings of STRAP’s role in neuroblastoma, we established an additional CRISPR-Cas9 stable knockout of STRAP in SK-N-BE human neuroblastoma cells." (PMID 34206917, 2021). "Using CRISPR-Cas9 gene editing technology, we established a stable cell line of STRAP KO cells in the neuroblastoma cell line SK-N-AS." (PMID 34206917, 2021). "In order to further validate the role of STRAP in these functions, we performed the same experiments in an additional neuroblastoma cell line, BE, with stable STRAP CRISPR-Cas9 KO." (PMID 34206917, 2021). "Using CRISPR-Cas9 gene editing technology, we established stable STRAP KO cells in two neuroblastoma cell lines, AS and BE." (PMID 34206917, 2021). "These previous studies supported the investigation of the potential for oncogenic function of STRAP in neuroblastoma." (PMID 34206917, 2021). "Due to the potential for off-target effects seen with si/shRNA technology, we wished to determine the effect of decreased STRAP on the neuroblastoma cell phenotype following knockout of the STRAP gene." (PMID 34206917, 2021). "In the current study, we demonstrated that STRAP knockdown decreased neuroblastoma proliferation, growth, and motility." (PMID 34206917, 2021). "The data presented in the current study provide evidence that the inhibition of STRAP led to decreased neuroblastoma viability, proliferation, and motility in vitro and decreased tumor growth in vivo." (PMID 34206917, 2021). "Studying the effects of STRAP knockdown in combination with neuroblastoma chemotherapeutics will be an exciting avenue of future studies." (PMID 34206917, 2021). "In order to evaluate the effect of STRAP KO on neuroblastoma at the transcriptomic level, we utilized RNA-seq to investigate changes in gene expression in AS STRAP KO compared to AS WT cells." (PMID 34206917, 2021). "Similar to results described in other in vivo studies, we demonstrated that the genetic knock out of STRAP resulted in decreased neuroblastoma tumor growth with significantly decreased proliferation in the KO tumors." (PMID 34206917, 2021). "In the current study, we demonstrate that the knockdown and knockout of STRAP resulted in a decrease in the malignant phenotype in neuroblastoma." (PMID 34206917, 2021). "Similar to the in vitro studies AS STRAP KO tumors exhibited decreased protein expression of PDGFRβ, which is known to promote tumor growth in neuroblastoma." (PMID 34206917, 2021). "The recent discovery of the role of STRAP in another pediatric solid tumor, osteosarcoma, and the known function of STRAP in neural development, led us to investigate the role of STRAP in neuroblastoma tumorigenesis." (PMID 34206917, 2021).
neuroblastoma (continued). "In addition to neuroblastoma, STRAP has also been found to be increased in various osteosarcoma cell lines (MNNG-HOS, 143B, and MG63), which is correlated to their oncogenic phenotype." (PMID 40558481, 2025). "We wished to determine if STRAP KD affected neuroblastoma proliferation." (PMID 34206917, 2021). "Similarly, we found that shRNA-mediated stable knockdown of STRAP resulted in decreased neuroblastoma cell proliferation, growth, and motility." (PMID 34206917, 2021). "We hypothesized that inhibition of STRAP protein expression in neuroblastoma would result in a decrease in the malignant phenotype in vitro and in vivo." (PMID 34206917, 2021). "We sought to determine whether STRAP functions assisted to promote the malignant phenotype in neuroblastoma and could provide a potential target for future therapies." (PMID 34206917, 2021). "In order to determine whether neuroblastoma cell motility was affected by STRAP KD, we utilized modified Boyden chamber assays to assess migration and invasion." (PMID 34206917, 2021). "Therefore, we wished to determine if STRAP played a role in maintaining a stem cell-like phenotype in neuroblastoma." (PMID 34206917, 2021). "Immunoblotting confirmed the presence of STRAP in five long-term passage neuroblastoma cell lines." (PMID 34206917, 2021). "Therefore, the inhibition of these oncogenic signaling pathways observed with STRAP KO provides support for the inhibition of STRAP in neuroblastoma as a therapeutic strategy." (PMID 34206917, 2021). "These discoveries lend support for investigating STRAP in neuroblastoma." (PMID 34206917, 2021). "Due to the more rapid growth rate of the AS cell line versus BE, the focus of our phenotypic studies on STRAP were performed using AS cells to optimize experimentation and to produce the important conclusions discussed in this paper on the role of STRAP in neuroblastoma." (PMID 34206917, 2021). "STRAP inhibition with shRNA technology decreased neuroblastoma motility." (PMID 34206917, 2021). "Overexpression of STRAP increases the activation (through phosphorylation) of Focal Adhesion Kinase (FAK), a non-receptor protein tyrosine kinase, and promotes the growth and metastasis of neuroblastoma cells." (PMID 40558481, 2025). "STRAP upregulation in epithelial tumors regulates several signaling pathways, such as TGF-ß, MEK/ERK, Wnt/β-Catenin, Notch, PI3K, NF-κB, and ASK-1 in human cancers, including colon, breast, lung, osteosarcoma, and neuroblastoma." (PMID 40558481, 2025). "The role of STRAP in pediatric malignancies and specifically in neuroblastoma has not been explored." (PMID 34206917, 2021). "We wished to determine whether the absence of STRAP would similarly affect the motility of neuroblastoma cells." (PMID 34206917, 2021). "We initially investigated the knockdown of STRAP by utilizing siRNA in two neuroblastoma cell lines, which are AS (MYCN non-amplified) and BE (MYCN amplified), and found that STRAP knockdown resulted in decreased proliferation." (PMID 34206917, 2021).